METTL3 (methyltransferase 3, N6-adenosine-methyltransferase complex catalytic subunit)
Diseases named in the same sentence as METTL3 in open-access papers (continued):
Sharing a sentence is not in itself a finding about the gene and the disease.
adenomyosis (7 papers, 2020 to 2025). The growth of endometrial tissue inside the muscular wall of the uterine corpus. "Mouse models of adenomyosis were constructed to determine the role of ferroptosis and METTL3 in vivo." (PMID 40911580, 2025). "Immunofluorescence imaging demonstrated that the ectopic endometrium in mice exhibited lower expression levels of GPX4 and METTL3 in the adenomyosis group." (PMID 40911580, 2025). "Through our research, we have elucidated a comprehensive pathway delineating how METTL3 modulates ferroptosis in the context of adenomyosis." (PMID 40911580, 2025). "METTL3 and m6A can also contribute to the differentiation of stem cells in different tissues, indicating another possible role of m6A and METTL3 in adenomyosis." (PMID 32719721, 2020). "The protein level of METTL3 appeared lower in myometrium of women with adenomyosis compared with controls (p = 0.198)." (PMID 32719721, 2020). "The protein level of METTL3 was significantly decreased in the endometrium of adenomyosis patients when compared with control (p = 0.034), consistent with its mRNA level." (PMID 32719721, 2020). "After combing the results from the bioinformatics analyses, m6A levels and METTL3 were considered as likely functional regulators in endometrium of women with adenomyosis." (PMID 32719721, 2020). "Moreover, the ferroptosis inducer erastin and METTL3 inhibitor exacerbated the uterine developmental disorder in the adenomyosis group." (PMID 40911580, 2025). "Thus, increased IGF1 in eutopic endometrium may mediate the regulation of METTL3 and contribute to the endometrial dysfunction in adenomyosis women through EMT." (PMID 32719721, 2020). "The western blotting results were consistent with human specimens, indicating a downregulation of METTL3 and GPX4 in adenomyosis." (PMID 40911580, 2025). "RNA methylation has also been implicated in reproductive system diseases, with decreased levels of methyltransferase-like 3 (METTL3) and N6-methyladenosine (m6A) observed in adenomyosis." (PMID 39595579, 2024). "From the analysis of the gene expression profile of GSE78851, we found that METTL3, ZC3H13, FTO, and YTHDC1 were all significantly decreased in the eutopic endometrium of adenomyosis patients versus controls." (PMID 32719721, 2020). "In conclusion, we speculate that m6A regulates the expression of METTL3 and downstream genes, activating AKT to affect cell proliferation and migration and thereby promoting the establishment of adenomyosis." (PMID 39595579, 2024).
asthma (7 papers, 2023 to 2025). "Conversely, METTL3 deficiency can mitigate asthma severity by negatively regulating the NF-κB pathway and thereby limiting M1 macrophage activation." (PMID 41515964, 2025). "Clinical and experimental evidence consistently indicates that reduced METTL3 expression is associated with increased disease severity in Th2-dominant asthma, highlighting the potential of m6A-dependent METTL3 activity as a therapeutic target for allergic airway inflammation." (PMID 41515964, 2025). "Interestingly, METTL3 exerts protective or pathogenic effects across asthma endotypes." (PMID 41515964, 2025). "By upregulating GPX4, METTL3 inhibits ferroptosis in bronchial epithelial cells, which promotes cell survival, proliferation, and alleviates asthma symptoms." (PMID 41008562, 2025). "Clinical Implications (Asthma): Targeting the METTL3 axis in neutrophilic severe endotypes presents an opportunity for combination strategies incorporating anti-NET therapies and metabolic modulators." (PMID 41515964, 2025). "Overall, current evidence supports a context-dependent dual role of METTL3 in asthma (predominantly protective in Th2-dominant allergic asthma, but potentially pathogenic in neutrophilic endotypes)." (PMID 41515964, 2025). "METTL3 suppresses M2 macrophage activation and subsequent asthma development through the PI3K‐AKT and JAK‐STAT6 signaling pathways." (PMID 41316520, 2025). "These structural motifs mainly METTL3′s Rossmann fold and zinc finger (ZF) domains are functionally relevant to asthma, as they enable specific m6A deposition on epithelial transcripts such as GPX4." (PMID 41008562, 2025). "Together, these findings highlight the context-dependent roles of METTL3 in different asthma subtypes and immune cell types." (PMID 41515964, 2025). "Our preliminary experiments have revealed that METTL3 was significantly upregulated in the peripheral blood of asthmatic children, suggesting a potential role of METTL3 in asthma." (PMID 39867638, 2025). "Although direct evidence for METTL14′s role in ferroptosis and Th2 immunity in asthma is limited, its scaffolding function is essential for guiding METTL3-mediated m6A deposition on inflammation- and epithelium-related transcripts." (PMID 41008562, 2025). "In T2 asthma, a marked decrease in METTL3 expression was observed at clinical, cellular, and animal levels, correlating with increased disease severity and airway inflammation." (PMID 41008562, 2025). "The overexpression of METTL3 in asthma models helps to increase the m6A modification of GPX4, a key protein that protects cells from ferroptosis (a type of cell death)." (PMID 41008562, 2025). "METTL3-m6A regulates Th1 and Th17 differentiation and activity, and its role in NA asthma inflammatory subtypes should be explored in depth." (PMID 39108751, 2024). "Mechanistically, m6A-sequencing shows that loss of METTL3 impairs the m6A-YTHDF3-dependent degradation of PTX3 mRNA, while higher PTX3 expression positively correlates with asthma severity through promoting M2 macrophage activation." (PMID 37957139, 2023). "Here the authors show that METTL3 is reduced in childhood asthma patients and that conditional knockout of Mettl3 in mouse myeloid cells enhances Th2 response and allergic asthma associated with changes in macrophage function." (PMID 37957139, 2023). "To investigate the expression pattern of METTL3 in allergic asthma, we first analyzed microarray datasets from 5 human asthma patients and 5 healthy controls from the GEO database (GSE27876)." (PMID 37957139, 2023). "In another study, the expression of METTL3, T-bet, and GATA3 was distinguished in bronchial epithelial cells from human and mouse asthma models, and METTL3 increased Th2 differentiation and inhibited Th1 differentiation." (PMID 37328853, 2023). "Therefore, METTL3 overexpression plays a protective role in asthma by preventing ferroptosis and supporting cell function." (PMID 41008562, 2025).
asthma (continued). "Low METTL3 levels promote inflammation and exacerbate asthma by activating M2-type macrophages." (PMID 41008562, 2025). "Additionally, METTL3 has been implicated in asthma progression through its involvement in DNA damage pathways, particularly via an exosomal lncRNA-mediated PAET-METTL3-YTHDF3-COX4I1 axis, which promotes DNA damage and worsens childhood asthma symptoms." (PMID 41515964, 2025). "Moreover, METTL3 suppresses PDGF-BB-induced airway smooth muscle cell (ASMC) proliferation and migration by downregulating the expression of TIMMDC1 suggesting a potential regulatory role in airway remodeling associated with asthma." (PMID 41515964, 2025). "Animal studies revealed that the reduced levels of asthma-associated inflammatory factors IL-6 and IL-12 mRNA in DC cells knocked down for METTL3 may have been related to a defective TLR4/NF-κB signaling pathway caused by the deletion of METTL3." (PMID 39108751, 2024). "Thus, the ability of monocyte-derived macrophages METTL3 abundance to differentiate childhood asthma patients from healthy participants was firstly assessed by receiver operating characteristic (ROC) curve analysis, yielding area under the curve (AUC) values of 0.79." (PMID 37957139, 2023). "Additionally, the m6A RNA modification machinery including METTL3, METTL14, FTO, YTHDF1/2, IGF2BP2, and WTAP is explored for its emerging significance in regulating post-transcriptional gene expression during asthma progression." (PMID 41008562, 2025). "In immune cells, METTL3 modulates Th2 differentiation, macrophage polarization, neutrophil activation and NET formation, thereby linking m6A modification to distinct inflammatory endotypes in asthma and infection related lung injury." (PMID 41515964, 2025). "Moreover, the METTL3/miR-192-5p/SCD1 signaling axis regulates lipid metabolism, thereby affecting T cell differentiation and contributing to the pathogenesis of asthma." (PMID 41515964, 2025). "The results showed that the expression of known m6A writers (i.e., METTL3 and METTL14), erasers (i.e., FTO and ALKBH5), and readers (i.e., YTHDF3) was moderately downregulated in peripheral blood mononuclear cells (PBMCs) of human asthma sufferers." (PMID 37957139, 2023). "To further examine whether the accelerated airway inflammation in Mettl3 KO mice was related to the neutrophils, we depleted the neutrophils in CRE-induced asthma models by injecting anti-Ly6G Ab." (PMID 37957139, 2023). "Additionally, silencing METTL3 in antigen-presenting HBE cells enhanced Th2 cell differentiation, underscoring METTL3′s critical role in regulating the immune response and airway inflammation in T2 asthma." (PMID 41008562, 2025). "Considered together, the m6A regulators YTHDF3, YTHDC1, WTAP, FTO, METTL3, and ETTL14 may have a significant effect on the prognosis of asthma, but studies on m6A methylation, severe asthma, and the prognosis of asthma are still in the initial stage and require further exploration by researchers." (PMID 39108751, 2024). "m6A-seq and MeRIP-qPCR findings indicate that m6A /METTL3/YTHDF3 interactions are involved in the repression of M2 macrophage activation by accelerating the degradation of Pentraxin 3 (PTX3) transcripts, which is widely regarded as a regulator of inflammation and asthma." (PMID 37957139, 2023).
breast tumor (7 papers, 2021 to 2025). "Metformin repressed breast tumor growth via the inhibition of METTL3, a methyltransferase known for inducing tumor cell proliferation via the miR-483-3p pathway." (PMID 38543182, 2024). "For instance, the m6A methyltransferase METTL3 upregulates HBXIP expression by inhibiting the tumor suppressor gene let-7g through m6A methylation, forming a positive feedback loop (HBXIP/let-7g/METTL3/HBXIP) that promotes cancer cell proliferation in breast tumors." (PMID 39473440, 2024). "In this study, we describe a cleaved form of METTL3, METTL3a, that is essential for the METTL3–WTAP interaction and m6A deposition, resulting in the promotion of breast tumor progression." (PMID 37589705, 2023). "High level of METTL3 upregulates HBXIP expression that inhibits the tumour suppressor let-7g through m6A methylation, and the positive feedback loop HBXIP/let-7g/METTL3/HBXIP promotes cancer cell proliferation in breast tumours (Ref." (PMID 33787478, 2021). "Furthermore, western blot revealed that the protein levels of METTL3, METTL14, and FTO were significantly lower in seven breast tumor samples randomly selected from RT-qPCR samples, while YTHDF1 and YTHDF3 had higher protein expression compared to adjacent tissues." (PMID 34804948, 2021).
Cerebral ischemia (7 papers, 2022 to 2025). Restriction of arterial blood supply to the brain associated with insufficient oxygenation to support the metabolic requirements of the tissue. "Collectively, our findings indicated that the neuroprotective effect of CAT against cerebral ischemia was associated with the inhibition of autophagy via the NRF1/KAT2A/METTL3/Beclin-1 axis." (PMID 38773376, 2024). "For example, METTL3 activity shapes axonal regrowth, neuronal survival, neurogenesis, and the neuroinflammatory response following cerebral ischemia." (PMID 41154582, 2025). "To elucidate the role of METTL3 in m6A modification during cerebral ischemia–reperfusion injury, we assessed m6A levels in the brains of Sham and MCAO/R mice." (PMID 41154582, 2025). "Increasing data present that METTL3 is an m6A transferase that plays a protective role in cerebral ischemia." (PMID 38773376, 2024). "CAT activated the NRF1/KAT2A/METTL3 axis and downregulated Beclin-1 expression, thus relieving neuronal injury and excessive autophagy after cerebral ischemia." (PMID 38773376, 2024). "Taken together, these in vivo data definitively confirm that METTL3 mediates neuroprotection in cerebral ischemia through modulating the NEDD4L-TFRC axis to suppress iron-induced ferroptosis." (PMID 38302612, 2024). "Collectively, our findings strengthen the concept that a “METTL3–m6A–lncRNA–reader” cascade constitutes a critical layer of post-stroke regulation and highlight lncRNA-centred epitranscriptomic networks as promising therapeutic targets for cerebral ischemia–reperfusion injury." (PMID 41154582, 2025). "Previous results also demonstrated that BBR exerts neuroprotective effects via the m6A methyltransferase METTL3, which regulates the NEAT1/miR-377-3p/Nampt axis in mouse astrocytes to ameliorate cerebral ischemia/reperfusion injury." (PMID 40829428, 2025). "Taken together, our results demonstrate that berberine exerts neuroprotective effects via the m6A methyltransferase METTL3, which regulates the NEAT1/miR-377-3p/Nampt axis in mouse astrocytes to ameliorate cerebral ischemia/reperfusion (I/R) injury." (PMID 38180752, 2024). "In a study exploring the relationship between m6A and circRNAs in mouse cerebral ischemia, the expression of YTHDF3 decreased and then increased, while the expression of METTL3 decreased." (PMID 38632288, 2024). "As a result, the present study revealed that CAT, the main active component of Rehmannia, protected against cerebral ischemia in vivo and in vitro by inhibiting neuronal injury and autophagy via the NRF1/KAT2A/METTL3/Beclin-1 axis." (PMID 38773376, 2024). "Collectively, the present findings show that berberine exerts neuroprotective effects via the m6A methyltransferase METTL3, which regulates the NEAT1/miR-377-3p/Nampt axis in mouse astrocytes to ameliorate cerebral ischemia/reperfusion injury." (PMID 38180752, 2024). "Overall, NRF1 activated METTL3 transcription via KAT2A, which may play a protective role in cerebral ischemia." (PMID 38773376, 2024). "Moreover, bioinformatics data and experimental results implied that NRF1 activated METTL3 transcription via KAT2A, which assumed a neuroprotective role in cerebral ischemia." (PMID 38773376, 2024). "On this basis, we conjectured that NRF1 may activate METTL3 transcription by promoting KAT2A transcription and increasing H3K27 acetylation level in METTL3 promoter region, thus playing a protective role in cerebral ischemia." (PMID 38773376, 2024). "Accordingly, we analyzed the mechanism of CAT in cerebral ischemic via the NRF1/KAT2A/METTL3/Beclin-1 axis with the focus on neuronal injury and autophagy, aiming to offer a theoretical basis for the development of CAT as neuroprotective drugs for the prevention and treatment of cerebral ischemia." (PMID 38773376, 2024).
chronic kidney disease (7 papers, 2022 to 2026). Impairment of the renal function secondary to chronic kidney damage persisting for three or more months. "Previous studies have shown that METTL3 plays a significant role in the development of polycystic kidney and chronic kidney disease, but there are few reports on its role in DKD." (PMID 40421968, 2025). "In this study, we show that the overall level of m6A methylated RNA was upregulated and the m6A methyltransferase METTL3 was induced in kidney tubular epithelial cells in mouse models and human kidney biopsies of chronic kidney disease (CKD)." (PMID 38904026, 2024).
endometrial tumors (7 papers, 2021 to 2025). "In endometrial tumors, reduced METTL3 expression or METTL14 mutation causes reduced levels of m6A, leading to enhanced cell proliferation, colony formation, migration, and invasion of tumor cells." (PMID 39457524, 2024). "In addition, ∼70% of endometrial tumors exhibited reductions in m6A methylation that are due to either METTL14 mutation (R298P) or decreased METTL3 expression." (PMID 34906165, 2021).